RPL17-C18orf32 (RPL17-C18orf32 readthrough)
Synonyms: PD-1
Gene: Protein-coding gene on chromosome 18 (49,481,681 to 49,492,479, reverse strand). Ensembl gene ENSG00000215472.
Genetic constraint (gnomAD): Loss-of-function variants: 7 observed, 33.95 expected, observed/expected ratio (o/e) 0.21, 90% interval 0.12 to 0.39. The upper end of that interval is the gene's LOEUF score, 0.39, which puts it in group 1 of 6, group 1 being the genes least tolerant of losing a copy. Missense variants: 198 observed, 290.88 expected, observed/expected ratio (o/e) 0.68, 90% interval 0.61 to 0.77. Synonymous variants: 108 observed, 100.62 expected, observed/expected ratio (o/e) 1.07, 90% interval 0.92 to 1.26.